MEF2A (myocyte enhancer factor 2A)
Diseases named in the same sentence as MEF2A in open-access papers (continued):
Sharing a sentence is not in itself a finding about the gene and the disease.
cancer (19 papers, 2009 to 2024). A tumor composed of atypical neoplastic, often pleomorphic cells that invade other tissues. "In another study on breast cancer, it was found that PTP4A3 can induce the transformation of normal cancer cells into stem-like cells by competitively binding to MEF2A with HDAC4 (histone deacetylase 4), a process independent of PTP4A3’s phosphatase activity." (PMID 38611852, 2024). "The identified TFs, such as FOXC1, FOXL1, POU2F2, NFIC, NFkB1, MEF2A, GATA2, and E2F1, are mainly associated with different types of cancers and congenital disorders." (PMID 37026010, 2023). "For instance, a recent study revealed that the transcription of CTNNB1 in cancer cells was mediated by MEF2A, which can be occupied by KMT2D." (PMID 35477537, 2022). "Further, we measured the protein levels of cancer cell metastasis-related markers (E-cadherin and vimentin) and the genes of interest (MEF2A and LEF1) were measured." (PMID 34957213, 2021). "We next evaluated the correlation between SEC23A expression and MEF2A or Hspa12a in Pan-cancer patients and prioritized MEF2A for biological validation." (PMID 34456965, 2021). "In patients with LCC or SCLC, the expressions of MEF2A were significantly lower, compared with non-cancer tissues (p < 0.01, and 0.001, respectively)." (PMID 28340574, 2017). "Moreover, western blot assay verified that MEF2A expression is lower in RCC carcinoma than in para‐carcinoma tissues." (PMID 37859585, 2023). "Identification of MEF2A as an essential transcriptional regulator of IFN I synthesis that is targeted negatively by PGE2 may pave the way for development of anti-cancer agents." (PMID 34129840, 2021). "Maintaining high levels of acetylated MEF2A and histones upregulates the expression of the stem cell key transcription factor SOX2, ultimately inducing cancer cell transformation into stem-like cells." (PMID 38611852, 2024). "To observe the impact of MEF2A on RCC progression, we injected RCC cells into mice to assess the correlation between MEF2A overexpression and cancer growth in vivo." (PMID 37859585, 2023). "For instance, it will be critical to investigate the role of MEF2A in controlling IFN I induction in vivo during infection, tissue damage, or cancer." (PMID 34129840, 2021). "In patients with NSCLC, the expressions of MEF2A and MEF2D were significantly higher, compared with non-cancer tissues (p < 0.01 and 0.001, respectively)." (PMID 28340574, 2017). "Seven cofactors (TFAP2A, E2F, GSTM1, IL6, PATZ1, MEF2A and GTF2I) identified in two of the five cancer types have general functions in cancers." (PMID 28684851, 2017). "We predict the differential expression of several transcription regulator genes (including HSF2, ARNT, MEF2A, ATF2 and YY1) that are strongly related to the cancer grade." (PMID 20025723, 2009). "Transforming growth factor (TGF)-β plays a role in the invasion, metastasis and growth of cancer cells by promoting HDAC degradation and histone hyper-acetylation at the MEF2 site of the matrix metalloproteinase (MMP-10) promoter, and by activating MEF2A and up-regulating the expression of MMP-10." (PMID 37008050, 2023). "The roles of MEF2A and MITF have not been previously characterized in these cancers and may present promising targets for study and potentially for therapeutic intervention." (PMID 31554806, 2019).
cardiovascular disease (11 papers, 2008 to 2024). "Functional deletion or mutation in MEF2A predisposes individuals to cardiovascular disease mainly caused by vascular endothelial dysfunction." (PMID 30885136, 2019). "To reveal whether plasma MEF2A levels decreased with age or were associated with the risk of cardiovascular disease, we measured plasma MEF2A levels in individuals in the CAD and normal control groups." (PMID 31182679, 2019). "Accordingly, we became curious about possible MEF2A involvement in vascular endothelial cell (VEC) aging by regulating the PI3K pathway, and whether the plasma levels of MEF2A can indicate risk of cardiovascular diseases such as CAD." (PMID 31182679, 2019). "Genotyping of MEF2A and SLC22A3-LPAL2-LPA polymorphisms was conducted to examine their effects on warfarin efficiency and cardiovascular disease susceptibility using PCR-based methods." (PMID 37948393, 2023). "This study aims to investigate the influence of MEF2A and SLC22A3-LPAL2-LPA polymorphisms on cardiovascular disease susceptibility and responsiveness to warfarin medication in Jordanian patients, during the initiation and maintenance phases of treatment." (PMID 37948393, 2023). "In recent years, the research on the function of MEF2A has rekindled the hope of MEF2A in the field of cardiovascular disease." (PMID 35047575, 2021). "The important role of MEF2A in neural differentiation, maturation and synapsis has been supported by a great deal of evidence, but its role in cardiovascular disease is still controversial." (PMID 35047575, 2021). "MEF2A and SLC22A3-LPAL2-LPA have been studied widely in their correlation with cardiovascular diseases in multiple ethnicities and have been both identified as risk factors for cardiovascular diseases." (PMID 37948393, 2023). "Therefore, our findings revealed the potential role and molecular mechanism of MEF2A in cardiovascular disease and provided a new perspective for further research on the pathological mechanism and prevention of senile diseases such as cardiovascular diseases." (PMID 31182679, 2019). "One SNP (SLC22A3-LPAL2-LPA rs10455872) has been associated with cardiovascular disease in the Jordanian population, whereas the other SNPs in the MEF2A gene and SLC22A3-LPAL2-LPA gene cluster did not have any significant differences between cardiovascular patients and healthy individuals." (PMID 37948393, 2023). "We also found that the plasma MEF2A level was negatively correlated with CAD and age in the present study, which further indicated the importance of normal expression of MEF2A in the prevention of cardiovascular diseases and other senile diseases." (PMID 31182679, 2019). "MEF2A functional deletion carriers were subjected to premature CAD, strongly supporting the important roles of MEF2A in providing protection against cardiovascular disease." (PMID 30885136, 2019). "However, there is no report stating the correlation between MEF2A and SLC22A3-LPAL2-LPA polymorphisms in Jordanian cardiovascular disease patients and warfarin responsiveness." (PMID 37948393, 2023).
infection (4 papers, 2015 to 2021). The state of being infected such as from the introduction of a foreign agent such as serum, vaccine, antigenic substance or organism. "We noticed an upregulation of the HATs p300, CBP and p/CAF, as well as TFs, pCREB and MEF-2A upon infection." (PMID 25809782, 2015). "shMEF2A dramatically reduced MEF2A levels five days after infection." (PMID 29588465, 2018). "Interestingly, upon infection, the interaction of MEF-2A with HDAC9 was expectedly diminished since HDAC9 binds to the C-terminal TAD domain of MEF-2 to repress its transcriptional activity." (PMID 25809782, 2015). "These cells showed efficient recruitment of MEF-2A and other cellular factors to the LTR upon infection." (PMID 25809782, 2015). "Infection of rat skeletal muscle with Ad-PIMT EGFP resulted in a robust decrease in the transcript levels of GLUT4, MEF-2A and MEF-2D." (PMID 26468734, 2015). "Importantly, infection with Ad-PIMT or Ad-PIMT Ser298Asp but not PIMT Ser298Ala resulted in a dramatic reduction of MEF2A and MEF2D expression in L6 myotubes." (PMID 26468734, 2015). "Consistent with the data from cultured cells, infection with Ad-PIMT Ser298Asp but not Ad-PIMT Ser298Ala suppressed GLUT4, MEF2A, MEF2D expression while up-regulating PGC1-α, HDAC5 and MEF2C expression in the rat skeletal muscle tissue." (PMID 26468734, 2015).
hematologic malignancies (2 papers, 2022 to 2024). "The genes belonging to the myocyte enhancer factor 2 (MEF2) family (MEF2-A, -B, -C, and -D) were characterized as oncogenes in hematologic malignancies." (PMID 39769169, 2024).
neurodegenerative disease (2 papers, 2019 to 2023). A disorder of the central nervous system characterized by gradual and progressive loss of neural tissue and neurologic function. "Abnormal expression and functional defects of MEF2A are often associated with neurodegenerative diseases." (PMID 37008050, 2023). "All of these highlight the potential of MEF2A as therapeutic target or biomarker for neurodegenerative disease." (PMID 37008050, 2023). "Chaperone mediated autophagy (CMA) targets MEF-2A to the lysosomes for CMA degradation, and stress-induced destabilization of the lysosome results in the disruption of MEF-2A and its function thereby leading to neuronal damage in various neurodegenerative diseases." (PMID 31105874, 2019).
neurological diseases (2 papers, 2024). "Recent studies have implicated GLS, RAI1, GIPC1, MED15, EP400, MEF2A, and CNKSR2 in neurological diseases, with GLS, GIPC1, MED15, RAI1, and MEF2A sharing the same repeat loci reported in this study." (PMID 38871700, 2024).
MEF2A also shares sentences with these, for which no sentence is quoted: Hypertension (2 papers); schizophrenia (2); acute coronary syndrome (1); acute monocyte leukemia (1); age-related macular degeneration (1); Ataxia (1); autosomal dominant hypocalcemia (1); branchiooculofacial syndrome (1); cerebral infarction (1); Cerebral ischemia (1); chronic myeloid leukemia (1); endometriosis (1); familial hypercholesterolemia-1 (1); glaucoma (1); Holt-Oram syndrome (1); hypercoagulability (1); hypertriglyceridemia (1); irritable bowel syndrome (1); ischaemic heart disease (1); ischemia (1); ischemic stroke (1); liver fibrosis (1); lymphoma (1); metabolic disease (1); metabolic syndrome (1); myelogenous leukemia (1); Myocardial fibrosis (1); myopathies (1); osteosarcoma (1); Peritoneal Fibrosis (1).
A further 6 diseases each share a sentence with MEF2A in 1 paper.